IL6 (interleukin 6)
Diseases named in the same sentence as IL6 in open-access papers (continued):
Sharing a sentence is not in itself a finding about the gene and the disease.
endotoxemia (continued). "In Candida-Bil Nep, probiotics improved survival rate, serum IL-6 (not TNF-α and IL-10), endotoxemia, and bacteremia with increased fecal butyric acid." (PMID 36969207, 2023). "The ability of SM to significantly enhance the IL-6-stimulating effect of LPS, revealed in RAW264.7 macrophages in vitro, was also demonstrated by us in non-lethal LPS-induced endotoxemia in vivo." (PMID 33114200, 2020). "The anti-inflammatory effect of glucocorticoids in septic systemic inflammation is well documented, and in a previous experimental study of ours, we concluded that steroid treatment prior to endotoxemia had beneficial circulatory effects, which were not mediated by TNF-alpha, IL-6, or NO." (PMID 28101752, 2017).
Hepatic steatosis (282 papers, 2011 to 2026). Steatosis is a term used to denote lipid accumulation within hepatocytes. "In clinical studies, hepatic IL-6 was increased in patients with biopsy-proven NASH compared to those with hepatic steatosis or controls and was associated with the severity of the disease." (PMID 40794228, 2025). "Using a rat model fed with a choline-deficient (CD) diet, which causes hepatic steatosis, a study examined the effects of IL-6 on the lipid content of the liver and mitochondria as well as cell death." (PMID 38535313, 2024). "Evaluation criteria encompassed hepatic steatosis, damage, fibrosis, apoptosis, lipid peroxidation/oxidant stress indicators, and gene expressions linked to IL-6." (PMID 38535313, 2024). "They demonstrated an increase in weight change only in HFD-fed Tnfsf14−/− mice, which is also associated with adipocyte hypertrophy and liver steatosis, possibly due to an increase in hepatic lipase and IL-10 together with a decrease in IL-6." (PMID 38255789, 2024). "The pro-inflammatory IL-6 has a contentious function in the setting of hepatic steatosis, a risk factor for the development of NAFLD." (PMID 38535313, 2024). "Several studies also have announced that hepatic steatosis assessed by AAR is associated with increased production of interleukin-6 and other pro-inflammatory cytokines by hepatozytes and nonperynchymal cells." (PMID 36909318, 2023). "Elevated IL-6 levels are also observed in patients with metabolic dysfunction-associated fatty liver disease (MAFLD)." (PMID 33763027, 2021). "Increased IL-6 levels result in an enhanced risk of insulin resistance in patients with fatty liver disease." (PMID 34956171, 2021). "Hepatic steatosis is associated with increased levels of several inflammatory cytokines including IL-1 and IL-6." (PMID 32915853, 2020). "Previous studies showed that IL6 was associated with insulin resistance and enhanced obesity and liver steatosis in HFD-fed mice." (PMID 33282902, 2020). "IL6/STAT3-dependent molecular mechanisms driving hepatic steatosis and the pathological processes that cause NAFLD progression are still poorly understood." (PMID 30206377, 2018). "Reductions in adiponectin and elevations in TNFα and IL-6 have been linked to fatty liver development." (PMID 28929125, 2017). "Overall, our results suggest that both deficiency and excess of IL-6 can lead to similar effects, particularly in the context of fatty liver disease." (PMID 27333268, 2016). "It should be pointed out that IL-6 has been proven to be closely associated with the development of hepatic steatosis and inflammation." (PMID 26569409, 2015). "IL-6-deficient mice show a high predisposition to diet-induced hepatic steatosis, which is related to defects in the process of fatty acid oxidation." (PMID 26035386, 2015). "In addition, based on three-factor models, we found that a higher degree of hepatic steatosis in men was significantly associated with increased adipose tissue (%), and higher interleukin-6 concentration (pg/mL)." (PMID 38732626, 2024). "The results of the regression models in the male group showed that a higher degree of hepatic steatosis was significantly associated with an increased percent body fat, greater area of visceral fat in abdominal cross-section (cm2), and higher serum IL-6 levels." (PMID 38732626, 2024). "IL‐6 signalling, on the contrary, was found to play a protective role against the development of hepatic steatosis in methionine‐choline deficient diet‐fed mice, whereas it may exacerbate liver inflammation." (PMID 35713152, 2022). "TNF-α could induce SREBP1 expression, resulting in hepatic steatosis; IL-1β and IL-6 are involved in hepatic steatosis and inflammation, which causes hepatic disease." (PMID 35409071, 2022).
Hepatic steatosis (continued). "The necroinflammatory form of non-alcoholic hepatic steatosis might be implicated in cardiac dysfunctions through the release of different proinflammatory cytokines (C-reactive protein, IL-6, and TNF-α) with consequent cardiac alterations." (PMID 36211332, 2022). "However, at the same time, a pathogenic role for IL6 trans-signaling in hepatic steatosis has also been proposed." (PMID 33397952, 2021). "Interestingly, the repeated administration of human IL-6 to WT mice causes complete remission of the fatty liver diseases whereas the replacement of IL-6 in IL6-/- mice with fatty liver aggravates the steatosis." (PMID 27333268, 2016). "Furthermore, IL-6 in liver homogenates is closely associated with the degree of liver steatosis and may be a significant cytokine in non-alcoholic fatty liver disease (NAFLD)." (PMID 40282416, 2025). "Moreover, as serum AC16:0 and AC18:1 are reported to be positively correlated with TNFα and IL-6 and associated with fatty liver disease, these changes may indicate inflammation and poor metabolic health in the underweight women." (PMID 33201881, 2020). "Significant evidence suggests that inflammation, driven by elevated levels of serum tumor necrosis factor-α (TNF-α) and interleukin 6 (IL-6), is a crucial mechanism in high-fat diet-induced fatty liver and determines the severity of the condition." (PMID 40141836, 2025). "Post-mortem analyses included qPCR, Western Blotting, biochemical and microscopical assessments for hepatic steatosis and insulin resistance, hypothalamic and adipose tissue inflammation, and circulating lipid, leptin and IL-6 levels." (PMID 39754229, 2025). "In high-fat diet-induced hepatic steatosis, Kupffer cells polarize toward M1, producing pro-inflammatory cytokines such as Interleukin-1 (IL-1), Interleukin-6 (IL-6), tumor necrosis factor α (TumorNecrosisFactor-α, TNF-α), causing inflammation." (PMID 40650120, 2025). "Elevated IL-6 levels activate hepatic inflammatory signaling pathways, disrupt lipid metabolism, and promote hepatic steatosis, thereby facilitating the NAFLD." (PMID 40943380, 2025). "Our findings identified SNPs significantly associated with disease risk, demonstrated altered expression of immune (IL-6, IL-8), antioxidant (SOD3, HMOX1), and lipogenic (ACACA, FASN) genes, and confirmed hepatic steatosis via ultrasonography." (PMID 41012815, 2025). "TNF-α significantly exacerbates hepatic steatosis, while IL-6 potently activates lipogenic factors in hepatocytes." (PMID 40098962, 2025). "Among these, p38α plays a pivotal role, with macrophage p38α being instrumental in promoting hepatic steatosis and the inflammatory response by inducing the secretion of the pro-inflammatory cytokine IL-6 through the polarization of M1 macrophages." (PMID 40969371, 2025). "BALF IL-6 correlated positively with liver steatosis grade (r = 0.73, p = 0.03), while SEMA4D in BALF showed a strong inverse correlation with steatosis (r = −1.00, p < 0.01)." (PMID 40869413, 2025). "As expected, ketogenic feeding has resulted in hepatic steatosis in both vehicle- and IL-6-treated gp130F/F mice, while gp130∆adipo mice were protected from IL-6-induced steatosis." (PMID 40864559, 2025). "Recombinant IL-6 administration further confirmed this, as IL-6–treated adipocyte-specific gp130 knockout mice were also protected from KD-induced hepatic steatosis compared with control mice." (PMID 40864559, 2025). "Our data demonstrated that adipocyte IL-6-gp130 signaling regulates lipolysis to protect adipocyte-specific gp130 KO mice from KD-induced hepatic steatosis." (PMID 40864559, 2025). "PCO also attenuated hepatic steatosis and IL-6 expression and protected the kidneys against oxidative damage and cellular senescence." (PMID 40699753, 2025). "Hepatic steatosis is closely associated with chronic low-grade inflammation, characterized by elevated pro-inflammatory cytokines such as TNF-α, IL-6, and C-reactive protein." (PMID 40502403, 2025).
Hepatic steatosis (continued). "This inflammation, marked by imbalanced TNF-α, IL-6, adiponectin, and leptin, promotes hepatic steatosis and IR, a core NAFLD pathogenesis." (PMID 41334428, 2025). "In agreement, adipocyte-specific deletion of gp130 protected mice from KD-induced hepatic steatosis in response to recombinant IL-6 treatment." (PMID 40864559, 2025). "Histological analysis was performed to evaluate hepatic steatosis, fibrosis, as well as the levels of inflammatory cytokines (IL-6, TNF-α) and antioxidant markers (SOD, GSH)." (PMID 40717987, 2025). "In ob/ob and high‐fat diet‐induced obese mice, IL‐6 ameliorated fatty liver by inducing STAT3 phosphorylation, while in IL‐10 knockout mice, deficiency of IL‐6 or STAT3 led to steatosis and hepatocellular injury." (PMID 40066227, 2025). "Curcumin significantly lowered the hepatic value of IL-6 in C57BL/6 mice given an MCD diet, models illustrating the crucial function of IL-6 in progressing from fatty liver to cirrhosis or cancer." (PMID 41368575, 2025). "Following 12 weeks of supplementation of HC+HG, a notably high number of neutrophil counts, fatty liver changes, massive production of IL-6, ROS generation, and senescent-positive cells in the liver were observed." (PMID 40868990, 2025). "Consistently, we have observed adverse effects of HCD consumption on the liver, marked by high neutrophil infiltration, fatty liver changes, elevated ROS, and IL-6 production." (PMID 41011207, 2025). "It has been shown that ellagic acid can significantly down-regulate the levels of liver inflammatory factors NF-κB, TNF-α, IL-1β, and IL-6 in mice with fatty liver disease induced by AKT gene transfection." (PMID 39877634, 2025). "In the mdr2−/− mouse model, the deletion of il6 gene or blockade of IL-6 trans-signaling by the soluble gp130 form exacerbated hepatic steatosis, inflammation, chronic hepatitis, and hepatocarcinogenesis, suggesting the protective role of IL-6 signaling." (PMID 38890694, 2024). "Previous reports showed that hepatic IL-6 signaling had a protective role against hepatic steatosis progression while enhancing liver inflammation in mice." (PMID 38664334, 2024). "This assumption is supported by our results demonstrating hepatic steatosis and increased expression of proinflammatory cytokines (e.g., IL-6) leading to impaired glucose tolerance in the HFF group." (PMID 38590904, 2024). "Hepatic steatosis generated by the MCD diet was exacerbated but liver damage was reduced when MR16-1 blocked IL-6/GP130 signaling." (PMID 38535313, 2024). "Silymarin showed a decrease in liver malondialdehyde content, expression of FASN, TNFα, IL‐6, iNOS genes in liver and hepatic steatosis." (PMID 39324876, 2024). "When we fed KAL-Tg mice and wild-type (WT) mice with HFD, KAL-Tg mice exhibited extensive inflammation, injury, and fibrosis along with aggravated hepatic steatosis, and the expression of TNFα, interleukin-6 (IL-6), α-SMA, and collagen I was also increased." (PMID 38472195, 2024). "Both GW4869 and Imip treatments resulted in a significant suppression of IL-1b and IL-6 gene expression, reinforcing the anti-inflammatory effects of inhibiting sphingomyelinase pathways in the context of hepatic steatosis." (PMID 38474427, 2024). "A “Symbiter” containing 14 live probiotic strains of Acetobacter, Propionibacterium, Bifidobacterium, and Lactobacillus + Lactococcus improved tumor necrosis factor (TNF)-α, IL6, aminotransferase activity, and hepatic steatosis in NAFLD patients." (PMID 38398870, 2024). "Hepatic histology and immunohistochemistry (IHC) analysis revealed the higher efficacy of Raydel® policosanol over BOC Sciences policosanol to prevent HCD-provoked fatty liver changes, cellular senescence, oxidative stress, and interleukin (IL)-6 production." (PMID 39204207, 2024).
Hepatic steatosis (continued). "On the contrary, PCO1 exhibited a substantial hepatoprotective role by curtailing HCD-induced fatty liver changes, cellular senescent, reactive oxygen species (ROS), and interleukin-6 (IL-6) production." (PMID 38931381, 2024). "OSO-HDL also displayed a substantial hepatoprotective role by preventing CML-induced fatty liver changes, IL-6 production, and ROS generation." (PMID 38790634, 2024). "A study using a mouse NASH model revealed that the blockade of IL-6 signaling enhanced hepatic steatosis but improved liver injury." (PMID 37189422, 2023). "While IL-6 signaling blockade resulted in accelerated liver steatosis in a diet-induced NASH murine model, it also improved liver injury." (PMID 36768637, 2023). "After 12 weeks of treatment, inhibition of interleukin 6 (IL-6), interleukin 10 (IL-10), and C-reactive protein and improvement of hepatic steatosis were observed." (PMID 37111945, 2023). "Mitoquinone and ASA significantly reduced liver steatosis and inflammation by decreasing the expression of TNFα, IL-6, Serpinb3, and cyclooxygenase 1 and 2 and restoring the anti-inflammatory IL-10." (PMID 37107346, 2023). "A high IL-6 level was found to increase the risk of NAFLD52, and IL-23 was elevated in NASH patients and was suggested to be indirectly linked with hepatic steatosis and pro-inflammatory response in NAFLD53." (PMID 37286586, 2023). "IL6 has been identified as one of the independent prognostic factors for liver steatosis in obese individuals." (PMID 38170037, 2023). "p38α-deficiency in macrophages resulted in attenuated hepatic steatosis, due to reduced secretion of pro-inflammatory cytokines (TNF-α, CXCL10 and IL-6)." (PMID 36845555, 2023). "The biosynthesis of these compounds was negatively associated with inflammatory cytokines (IL-6, IL-23, and MCP-1) linked with hepatic steatosis and fibrosis in NAFLD52–55." (PMID 37286586, 2023). "On one hand, there is evidence that IL-6 exerts a hepatoprotective effect against liver steatosis due to the reduction of ROS generation and the subsequent oxidative stress attenuation." (PMID 36768637, 2023). "The rHDL containing Cuban policosanol inhibited acute inflammatory cascade via elevation of serum HDL-C and suppression of serum TG, AST, and ALT: the lowest neutrophil infiltration, fatty liver changes, ROS production, and IL-6 levels in hepatic tissue." (PMID 37764492, 2023). "There is a consensus that oxidative stress and inflammatory mediators such as TNF-α and IL-6, which are hallmarks of liver steatosis, can alter the function of nuclear receptors (NRs) in NAFLD." (PMID 35625421, 2022). "A differential expression of IL-13, G-CSF, CCL11, IL-6 and IL-4 among patients at different stages of hepatic steatosis, highlighted a possible role of an inflammatory response in the development of hepatic steatosis and fibrosis in CHB patients." (PMID 36544761, 2022). "The same method was used to feed IL-6 knockout and wild-type mice, with comparable levels of hepatic steatosis in HFD-fed IL-6−/− and HFD-fed WT mice." (PMID 36324678, 2022). "Activation of signal transducer and activator of transcription 3 (STAT3) by interleukin-6 protects against HFD-fed-induced fatty liver and alcoholic hepatitis." (PMID 35614477, 2022). "Hepatic steatosis and pro-inflammatory responses, such as those mediated by IL-6, are frequently accompanied by impaired glucose homeostasis." (PMID 35276798, 2022). "TNF-α and IL-6 induce adipogenesis and increase the production and secretion of TGs, which promote the development of hyperlipidemia and fatty liver disease." (PMID 35967316, 2022). "Conversely, chronic treatment of ob/ob mice with subcutaneous injection of recombinant IL-6 reduced hepatic steatosis and triglyceride levels." (PMID 34977118, 2021). "A significant increase in the level of IL-6 was also observed in patients with fatty liver, which would activate the innate immune cell cluster in the liver and drivers the progression of liver injury." (PMID 34602072, 2021).